STAB1 (stabilin 1)
Diseases named in the same sentence as STAB1 in open-access papers (continued):
Sharing a sentence is not in itself a finding about the gene and the disease.
tumor (continued). "The results of our study revealed that the clearance function of TAM in stabilin-1 ko mice was decreased and accompanied reduced tumor growth in vivo." (PMID 27105498, 2016). "We found that 21 days post-inoculation tumor size was decreased by 36% in stabilin-1 ko mice compared to wt mice." (PMID 27105498, 2016). "Overall, we suggest that modulation of tumor growth by stabilin-1 is mediated through dynamic removal of SPARC and presumably other unidentified tumor-regulating factors from extracellular space." (PMID 27105498, 2016). "Comparable levels of SPARC expression were detected in wt and stabilin-1 ko tumors suggesting involvement of SPARC in the regulation of TS/A tumor growth in both mouse strains." (PMID 27105498, 2016). "Immunohistochemical analysis of TS/A tumors on day 21 after tumor cell inoculation revealed abundant stabilin-1 expression in wild type (wt) mice." (PMID 27105498, 2016). "Potential effect of stabilin-1 knockout on infiltration of immune cells and angiogenesis was examined on day 21 of tumor growth." (PMID 27105498, 2016). "Overall, our data indicate that stabilin-1 is involved in the clearance and sequestration of tumor growth modulating factors such as SPARC from extracellular space." (PMID 27105498, 2016). "In order to examine the effect of stabilin-1 on tumor growth, Balb/c wt and stabilin-1 ko mice were injected subcutaneously with 5×106 TS/A tumor cells." (PMID 27105498, 2016). "In this study we have demonstrated that stabilin-1 endocytic ligand SPARC was indeed involved in induction of tumor cell death although its effect was moderate." (PMID 27105498, 2016). "STAB1 is predominantly expressed in alternatively activated macrophages, which exhibit multi-functional roles in cellular trafficking, endocytosis, immune modulation, and tumor progression." (PMID 41007347, 2025). "Blockade of STAB1 (with bexmarilimab) followed by transcriptomic analysis demonstrated that TAMs were reprogrammed to enhance production of IL1β, IFNγ, and TNFα; all pro-inflammatory and cytolytic killing of tumor cells." (PMID 41007347, 2025). "Furthermore, combining anti-STAB1 antibody with anti-PD-1 therapy synergistically reduced TAMs and improved efficacy in refractory tumor models of lung and colon cancers." (PMID 41007347, 2025). "Stabilin-1 is a scavenger receptor that is typical of pro-tumor macrophages." (PMID 40427136, 2025). "Also, a better understanding is needed of how STAB1 is involved in tumor growth, metastasis, immune modulation, and extracellular matrix remodeling." (PMID 41007347, 2025). "Furthermore, macrophage-specific genetic deletion stabilin-1 gene reduces tumour growth and metastatic spread." (PMID 39684877, 2024). "Altogether, this indicates that modulation of Stab1 might strongly depend on tumor- and organ-specific factors." (PMID 38275881, 2024). "The influence of Stab1 on tumor development has already been studied in several tumor models." (PMID 38275881, 2024). "Finally, we saw an increase in heterogeneity and proportion of anti-inflammatory Mɸ (AIMɸ), with a subset of cycling anti-inflammatory Mɸ, STAB1 + Mɸ and CAMLs being abundantly present in tumour tissue." (PMID 38782901, 2024). "We identified two tumor-specific ligands of Stabilin-1, SPARC and EGF." (PMID 39516356, 2024). "In line with trajectory analysis, CAMLs co-expressed many of the genes specific to STAB1 + Mɸ, supporting the hypothesis that CAMLs are likely derived from STAB1 + Mɸ following their close interaction with tumour cells." (PMID 38782901, 2024). "This suggests that the effects of a modulation of Stab1 depend on the tumor entity." (PMID 38275881, 2024). "Taken together, our analysis suggests that tumour macrophages, especially STAB1 + Mɸ, exhibited a transcriptional signature reminiscent of Mɸ during foetal lung development, suggesting that they have undergone oncofoetal reprogramming within the NSCLC tumour environment." (PMID 38782901, 2024).
tumor (continued). "Murine models suggest that the response to anti-Stab1 treatment is tumor- and organ-specific." (PMID 38275881, 2024). "The findings that stabilin-1 preferentially mediates the recruitment of Tregs and B cells could have significant implications for tumour development in the liver." (PMID 31315308, 2019). "Compared with C-MOs, MAMPCs expressed higher levels of TAM signature genes (i.e., Arg1, Cdh1, Hmox1, Il1r2, Mrc1, and Stab1) that were also highly expressed by MAMs, suggesting that differentiation of C-MOs to MAMPCs (M-MDSCs) is directed toward the tumor-promoting macrophages." (PMID 29387063, 2017). "Notably, with Ttl, S100a4, Zfx, Cct3, Stat3, Stab1 and Bmx, 7/20 found candidate genes have been reported as proliferation-related in tumor cells too." (PMID 29228606, 2017). "In addition, co-staining with pan-cytokeratin antibodies excluded tumor cells as a source of stabilin-1 expression." (PMID 27105498, 2016). "As a significant output, our study suggests the importance of stabilin-1-mediated silent ligand clearance in the modulation of tumor microenvironment as opposed to active clearance associated with changes in macrophage phenotype." (PMID 27105498, 2016). "Based on our own results and studies from other groups we conclude that stabilin-1 may be involved in progression of many types of cancer and appears to be potential target for anti-tumor immunomodulatory therapy." (PMID 27105498, 2016). "Therefore, all subsequent studies of the impact of stabilin-1 on tumor growth concerned the number and function of TAM." (PMID 27105498, 2016). "We cannot exclude that due to promiscuous ligand-binding ability of stabilin-1 uptake of unidentified tumor-regulating ligands in addition to SPARC may contribute to overall tumor promoting effect of stabilin-1." (PMID 27105498, 2016). "Interestingly, there was a clear relationship between low CLEVER-1/Stabilin-1+ vessel count and increasing tumor stage and higher grade." (PMID 26197470, 2015). "Thus, STAB1 upregulation in M2 macrophages might play a critical role in the invasiveness of tumor behavior and metastasis." (PMID 41007347, 2025). "Thus, targeting STAB1 in combination with existing immunotherapies could provide clinically relevant advancements in reducing primary tumor burden and metastases." (PMID 41007347, 2025). "Notably, the loss of STAB1 function did not affect B cell stimulation for antibody production but instead improved the humoral immune response against tumor antigens." (PMID 41007347, 2025). "The secreted version of STAB1 may be how this receptor signals to other cells via extracellular vesicles (EVs), microvesicles, or free protein in the plasma/interstitial fluid to modulate the immune profile in the tumor microenvironment." (PMID 41007347, 2025). "STAB1+ plays a pivotal role in facilitating the adhesion and engulfment of apoptotic cells by engaging in a specific interaction with phosphatidylserine, supporting the hypothesis of a strong interaction of a Mɸ with a tumour cell in CAMLs63." (PMID 38782901, 2024). "We validated the increase in omental tumour STAB1 expression in CT-treated mice using flow cytometry on CT-treated and control mice, concluding that mouse macrophages replicated most of the features of human macrophages clusters and response to CT with upregulation of Stab1." (PMID 39578450, 2024). "Therefore, we hypothesise that STAB1 + Mɸ might play a crucial role in supporting tumour progression by sustaining the increased iron requirement of highly-cycling tumour cells." (PMID 38782901, 2024). "Using CRISPR/Cas9, we inactivated Stabilin-1, and found that its absence affected neither tumor size nor epithelial characteristics but was associated with a decrease in the intratumoral CD4+/CD8+ T-cell ratio, thereby supporting a potential immunosuppressive role for the STABILIN-1 macrophages." (PMID 36230610, 2022).
tumor (continued). "Generally, a high expression of STAB1 in cancer patients of The Cancer Genome Atlas pan-cancer cohort (n = 11768) is significantly associated with reduced survival, regardless of patient characteristics, tumour type, therapy or clinical manifestations (left)." (PMID 32595212, 2020). "Therefore, we next asked whether new functions of stabilin-1 ko TAM might attenuate tumor growth in the TS/A tumor model." (PMID 27105498, 2016). "Their phenotype is shaped by tumor microenvironment towards immunosuppressive state associated with increased production of tumor growth-promoting cytokines, decreased antigen-presenting properties, and elevated expression of scavenger receptors (SR) including SR-A, CD206, CD163, and stabilin-1." (PMID 27105498, 2016). "Thus, we examined which cell type expresses stabilin-1 in TS/A tumor microenvironment." (PMID 27105498, 2016). "Among the most established biomarkers are members of the scavenger receptor family, such as CD206, CD163, stabilin-1, Marco, CD36, and CD204, which are expressed on CD68+ macrophages in tumor tissues." (PMID 41417432, 2025). "We previously showed that stabilin-1+ macrophages mediate efficient clearance of matricellular protein SPARC and contribute to tumor progression." (PMID 36960065, 2023). "In particular, the role of stabilin-1 in CRC is of interest, while total amount of TAMs in this cancer type, in contrast to majority of other types, correlates with reduced tumor growth and good prognosis." (PMID 36686729, 2022). "Our previous work already suggested that CD68+ TAMs can support tumor angiogenesis, primarily before NAC, while stabilin-1+ TAMs rather contribute to the maintenance of lymphatic vessel density after NAC." (PMID 34209679, 2021). "The expression of STAB1 in endothelial cells, lymphatic cells, and M2 macrophages in different organs and its role in tumor development is not fully characterized." (PMID 41007347, 2025). "Consequently, the clearance of SPARC via STAB1 contributes to the regulation of ECM organization and tumor characteristics in the TME." (PMID 41007347, 2025). "Normal mammary fat pads (MFPs) and tumor sections (n = 5 per group) were double-stained for Lyve-1 to identify single M-LECP cells and eight proteins known to promote cell fusion including CD36, CD98, CD209, Dap12, Dc-stamp, Sirp-a, Sirp-b1, and stabilin-1." (PMID 40507286, 2025). "Recently, the results from a phase I/II clinical trial show that STAB-1 blockade through the monoclonal antibody bexmarilimab leads to TAM reprogramming towards a pro-inflammatory phenotype, immune activation and tumor control in patients with late-stage cancer." (PMID 40433358, 2025). "This accumulating evidence highlights that STAB1+ might have a role in maintaining the complexity of TME and could play a critical role in the regulation of tumor growth and metastasis." (PMID 41007347, 2025). "Compared to non-treated mouse tumours, macrophages in CT-treated tumours showed significant upregulation of phagocytosis genes such as Stab1, Mrc1, Mertk and downregulation of ECM and angiogenesis such as Mmp9 and Col1a1." (PMID 39578450, 2024). "Tumor-supporting activity is related to facilitating tumor invasion, proliferation and migration (mediated by CD204, CD206, CXCL16, stabilin-1, and RAGE), M2-like TAM polarization (by CD36, LOX-1, CXCL16, CD163, and RAGE), and tumor angiogenesis (by CD68, Dectin-1, and RAGE)." (PMID 39516356, 2024). "As initial tumor cell adhesion and retention of B16F10 luc2 after spleen injection were not affected by deficiency of Stab1, the influence of Stab1 in the B16F10 luc2 model seems to be restricted to later phases of liver colonization." (PMID 38275881, 2024). "In a subcutaneous LLC1 Lewis lung adenocarcinoma model, mice lacking Stab1 expression in Mɸ, tumour growth was diminished." (PMID 38782901, 2024).
tumor (continued). "Thus, for the first time we identified that stabilin-1 acts as a scavenger receptor for internalization and endocytic trafficking of EGF, an essential regulator of tumor growth." (PMID 36960065, 2023). "Tumor-supporting activity mediated by macrophage SRs includes regulation of tumor invasion, proliferation and migration (for CD204, CD206, CXCL16, Stabilin-1, and RAGE), as well as M2-like TAM polarization (for CD36, LOX-1, CXCL16, CD 163, and RAGE) and tumor angiogenesis (for CD68, Dectin-1, RAGE)." (PMID 36686729, 2022). "Despite high similarity in domain organization and endocytic functions, stabilin-1, but not stabilin-2 is expressed on TAMs and plays an essential role in tumor development." (PMID 36686729, 2022). "In the PTC model used in this study, we did not observe STABILIN-1 expression on tumor vessels or changes in CD206+ macrophage populations upon Stabilin-1 inactivation." (PMID 36230610, 2022). "All these data demonstrate that homophylic interaction between EC and macrophage Clever-1/stabilin-1 is involved in TAM recruitment into tumor without affecting CD4+ or CD8+ lymphocyte recruitment." (PMID 33783686, 2021). "Further phenotypic characterization of stabilin-1 positive cells using monocyte/macrophage marker CD163 revealed that CD68+Stab-1+ TAM co-expressed CD163 in certain tumor areas whereas CD68−Stab-1+ cells were typically negative for CD163." (PMID 27105498, 2016). "The data demonstrated that stabilin-1 is expressed on CD68+ TAM in TS/A tumor tissue but not on CD31+ micro-vessels." (PMID 27105498, 2016). "Stabilin-1 mediates internalization of extracellular secreted protein acidic and rich in cysteine (SPARC), regulating its concentration and thereby promoting extracellular matrix remodeling, angiogenesis, and tumor progression." (PMID 23316105, 2012). "STAB1 levels were not significantly different between patients who received three versus six cycles of NACT or between BRCA mutated and HRD (BRCAm/HRD) tumours versus BRCA wild-type and non-HRD tumours (BRCA-WT)." (PMID 39578450, 2024). "We hypothesised blocking STAB1 could reduce lysosomal antigen degradation and improve antigen presentation after NACT which could repolarize macrophages towards an APC phenotype enhancing their anti-tumour role." (PMID 39578450, 2024). "By quantitative immunohistochemistry we found that cisplatin-based NACT has not resulted in the biologically significant decrease of total amount of CD68+ TAMs and amount of CD206+ and stabilin-1+ M2-like TAMs in the remaining tumor tissue compared to the non-treated tumor." (PMID 36960065, 2023). "Moreover, the absence of stabilin-1 in our model did not affect macrophage infiltration into the tumor mass." (PMID 27105498, 2016). "In addition, we found that stabilin-1 ko tumor-bearing BALB/c mice have reduced expression of PKCβ not only in TAM but also in peritoneal macrophages, as well as in liver and kidney." (PMID 27105498, 2016). "We and others also found in several tumor models that stabilin-1 is expressed by TAM, leading to the hypothesis that stabilin-1-mediated clearance of SPARC can affect tumor angiogenesis." (PMID 24634660, 2014). "Stabilin-1, a type-1 transmembrane receptor that mediates clearance of “unwanted self” components, is another marker for M2 macrophages that has been found to be expressed by TAM in several murine tumor models (e.g., B16 melanoma, pancreatic insulinoma, breast carcinoma)." (PMID 23316105, 2012). "The increase in STAB1 positive macrophages was seen in BRCA-WT and BRCAm/HRD tumours, however, was not significant in BRCAm/HRD group in the patient-matched cohort." (PMID 39578450, 2024). "Interestingly, previous studies could not clearly distinguish the effects of Stab1 between endothelial cells and macrophages, as only global Stab1 KO mice showed statistically significant effects on tumor growth reduction as compared to endothelial or macrophage-specific KO mice." (PMID 38275881, 2024).
tumor (continued). "The combination of anti-Stab1 and anti-PD1 treatments leads to increased levels of CD8+ T cells in murine tumors, with no additive effect on tumor reduction." (PMID 38275881, 2024). "Patients with high tumour macrophage STAB1 infiltrate post-NACT had significantly worse PFS and OS than patients with lower macrophage STAB1 levels (P = 0.0046 and P = 0.043) but this was not significant for pre-NACT STAB1 levels." (PMID 39578450, 2024). "We conclude that the absence of stabilin-1 in ko mice does not change the abundance of TAM and tumor vascularization." (PMID 27105498, 2016).